CCL17 (C-C motif chemokine ligand 17)
Diseases named in the same sentence as CCL17 in open-access papers (continued):
Sharing a sentence is not in itself a finding about the gene and the disease.
Granuloma (1 paper, 2015). A compact, organized collection of mature mononuclear phagocytes, which may be but is not necessarily accompanied by accessory features such as necrosis. "The expression levels of CXCL10, CXCL11, CCR7, CCL17 and CCL18 in the tuberculous granuloma were measured by quantitative real-time RT-PCR and were compared with the levels detected in lung tissues without granulomas." (PMID 26091535, 2015).
Graves disease (1 paper, 2023). Graves' disease is an autoimmune disorder that leads to overactivity of the thyroid gland (hyperthyroidism).It is caused by an abnormal immune system response that causes the thyroid gland to produce too much thyroid hormones. "In comparison between Graves' disease (GD) patients and controls, genotype frequency of CCL17(rs223828)CC(OR = 0.4) was lower in the GD group, whereas those of CCR2(rs1799864)AA(OR = 4.8) were higher in the GD group." (PMID 37730733, 2023).
head and neck carcinoma (1 paper, 2023). A carcinoma that arises from the head and neck region. "High expression levels of CCL22 and CCL17 are positively correlated with CD4+ T cell infiltration and a favorable prognosis with ICI treatment in patients with head and neck carcinoma." (PMID 38026978, 2023).
head and neck squamous cell carcinoma (1 paper, 2024). A squamous cell carcinoma that arises from any of the following anatomic sites: lip and oral cavity, nasal cavity, paranasal sinuses, pharynx, larynx, and salivary glands. "Studies on head and neck squamous cell carcinoma (HNSCC) have identified CCL22 and CCL17 as important prognostic factors for patient survival and response to immune checkpoint blockade therapy." (PMID 38791448, 2024).
hemorrhagic stroke (1 paper, 2025). A stroke caused by a bleed on the brain. "First, CCL17 can promote the infiltration of regulatory T cells (Tregs), which have been shown to suppress inflammatory responses and provide neuroprotection after hemorrhagic stroke." (PMID 39996481, 2025).
HIV-1 infection (1 paper, 2019). The type species of lentivirus and the etiologic agent of acquired immunodeficiency syndrome (AIDS). "Presented data shows that the chemokines, CCL17, CCL18, and CCL22 are increased during HIV-1 infection." (PMID 30979916, 2019). "Notably, plasma levels of the TH2 chemokines CCL17 and CCL22 are also elevated during HIV-1 infection." (PMID 30979916, 2019).
Hypercholesterolemia (1 paper, 2025). An increased concentration of cholesterol in the blood. "Together, these findings suggest that Tregs may migrate to peripheral LNs and atherosclerotic lesions partly via the CCL17/CCL22–CCR4 axes under hypercholesterolemia." (PMID 40608058, 2025).
Insulin resistance (1 paper, 2023). Increased resistance towards insulin, that is, diminished effectiveness of insulin in reducing blood glucose levels. "Here we report that compared with in control subjects, circulating chemokines CCL17 and CCL22 are significantly augmented in patients with morbid obesity and positively correlated with BMI and insulin resistance." (PMID 37124725, 2023).
lepromatous leprosy (1 paper, 2014). A chronic communicable infection which is a principal or polar form of leprosy. "Increased CCL18 levels were associated with lepromatous leprosy in randomly generated discovery and validation cohorts in 40/40 (100%) of the iterations, while increased CCL17 levels were associated with tuberculoid lesions in 29/40 (73%)." (PMID 25412496, 2014). "Patients with lepromatous leprosy had a non-significant trend (p = 0.16) of decreasing CCL17 levels and a significant trend (p = 0.036) of increasing CCL18 levels in the serum." (PMID 25412496, 2014).
liver diseases (1 paper, 2020). "In addition, the pathogenic role of other chemokines such as CCL2 (MCP-1), CCL17, CCL11, CCL20 and CXCL1 in liver diseases remains unclear and requires further investigation." (PMID 32641985, 2020).
lymphoid neoplasm (1 paper, 2023). A neoplasm composed of a lymphocytic cell population which is usually malignant (clonal) by molecular genetic and/or immunophenotypic analysis. "], elevated levels of TARC/CCL17 are not specific enough for the differential diagnosis of HES (e.g., for other lymphoid neoplasms)." (PMID 37122022, 2023).
mesothelioma (1 paper, 2025). A usually malignant and aggressive neoplasm of the mesothelium which is often associated with exposure to asbestos. "Significantly higher levels of multiple chemokines were expressed in R- vs NR- mesotheliomas, namely CCL5, CCL16, CCL17, CCL19, CCL21, CCL25, and CXCL14 Benajmini-Hochberg adjusted P values < 0.05." (PMID 40691143, 2025).
morbid obesity (1 paper, 2023). An excess of body weight, normally defined as an individual with a body mass index greater than 35 or a body weight greater than one hundred percent of ideal body weight. "Plasma levels of CCL17 were notably elevated in patients with morbid obesity (median, 67.8 pg/mL, range 16.6–185.6 pg/ml) compared with control subjects (median 51.8 pg/mL, range 22.2–84.5 pg/mL, p=0.029)." (PMID 37124725, 2023). "The aim of this study was to investigate the role of chemokine receptor CCR4 and its ligands CCL17 and CCL22 in human morbid obesity." (PMID 37124725, 2023).
myeloid leukemia (1 paper, 2022). A clonal proliferation of myeloid cells and their precursors in the bone marrow, peripheral blood, and spleen. "In our study, IL-4 could induce the expression of M2 markers including IL-10, TGF-β, and CD163 as well as some chemokines including CCL-17 and CCL-22 in human myeloid leukemia mononuclear THP-1 cells." (PMID 35996149, 2022).
myocardial infarction (1 paper, 2025). Gross necrosis of the myocardium, as a result of interruption of the blood supply to the area, as in coronary thrombosis. "An interesting study found that CCL17 and CCL22 can participate in the regulation of Treg chemotaxis as competitive biased ligands of CCR4 in myocardial infarction." (PMID 41266856, 2025).
onchocerciasis (1 paper, 2022). Onchocerciasis is a form of filariasis, caused by the parasitic worm Onchocerca volvulus, transmitted by the black fly. "In onchocerciasis patients at baseline, the OvAg-induced cytokine IL-10 production correlated positively with IFN-γ (R = 0.371, P = 0.0022), with CCL17 (R = 0.471, P < 0.0001) and with CCL18 (R = 0.322, P = 0.008)." (PMID 35503786, 2022).
ovarian tumor (1 paper, 2023). "Therefore, the role of CCL17 in the ovarian tumor microenvironment is worthy of further investigation." (PMID 37435088, 2023).
papilloma (1 paper, 2015). A benign epithelial neoplasm that projects above the surrounding epithelial surface and consists of villous or arborescent outgrowths of fibrovascular stroma. "The proposed mechanism of Treg recruitment is consistent with the data found in RRP which shows that CCL17 and CCL22 are produced by papilloma tissues and disseminated widely enough to be found in plasma." (PMID 26023354, 2015). "If it can be confirmed that LCs are the source of CCL17 and CCL22 in HPV 6 and 11-induced papillomas, it would suggest that LCs play an active role in creating and maintaining local immune suppression by recruiting T regulatory cells into HPV 6 and 11 infected epithelial tissues." (PMID 26023354, 2015).
periodontitis (1 paper, 2015). An acute or chronic inflammatory process that affects the tissues that surround and support the teeth. "Thus, it remains unclear whether CCL17 is likely to reduce or exacerbate inflammation in periodontitis." (PMID 25999952, 2015).
pneumocystis pneumonia (1 paper, 2018). "CD4+ T cells and STAT4/6, at least in a mouse model of pneumocystis pneumonia, are necessary for M2 macrophage MMP12 expression and RELM-α and CCL17 production." (PMID 29304863, 2018).
radiation pneumonitis (1 paper, 2009). Inflammation of the lung due to harmful effects of ionizing or non-ionizing radiation. "In our previous study, we showed that the production of CCL22 and CCL17 in rat radiation pneumonitis increased significantly, but CCL17 was undetectable in BAL fluid of IPF patients." (PMID 19715610, 2009).
renal cell carcinoma (1 paper, 2017). "Elevated serum level of CCL17 predicts better survival in renal cell carcinoma after peptide vaccination and melanoma carcinoma." (PMID 28178948, 2017).
respiratory syncytial virus infection (1 paper, 2018). "The Epstein-Barr infection of B cells induces the expression of CCL17/TARC, whereas the respiratory syncytial virus infection of Balb/c mice results in an increased CCL17/TARC production in the lung." (PMID 30140381, 2018).
Salmonella Infections (1 paper, 2021). Infections with bacteria of the genus SALMONELLA. "In summary, the present work broadens our knowledge of the phenotype and localization of CCL17‐producing cells in the context of Salmonella infection." (PMID 33945673, 2021). "In addition, the differential upregulation of CCL17 in distinct intestinal DC subsets in response to Salmonella infection was revealed." (PMID 33945673, 2021).
schizophrenia (1 paper, 2024). A major psychotic disorder characterized by abnormalities in the perception or expression of reality. "Among the 13 chemokines studied, a 7 week treatment with OLZ resulted in an increase in two homeostatic chemokines, BCL (CXCL13) and MDC (CCL22), and two inflammatory ones, KC (CXCL1) and TARC (CCL17), all of which were shown to take part in schizophrenia and other mental diseases." (PMID 39457671, 2024).
scleroderma (1 paper, 2025). Scleroderma is a rare autoimmune connective tissue disorder characterized by abnormal hardening of the skin and, sometimes, other organs. "The neutralizing antibody SAR156597 for IL-4 and IL-13, which directly induce CCL17, reduced the CCL17 levels in the plasma and exhibited significant improvement in the skin scores and a trend toward improved respiratory function in a phase II study of the multiorgan fibrosing disease scleroderma." (PMID 40269953, 2025).
scrub typhus (1 paper, 2014). Scrub typhus is a rare dust mite-borne infectious disease caused by the Orientia tsutsugamushi bacterium and characterized clinically by an eruptive fever which is potentially serious. "Interestingly, in addition to low levels of RANTES, low levels of sCD40L, MDC and CCL17 were also found to characterize scrub typhus compared with infectious disease controls, and all these mediators are released from platelets during activation." (PMID 24516677, 2014).
seminoma (1 paper, 2021). A radiosensitive malignant germ cell tumor found in the testis (especially undescended), and extragonadal sites (anterior mediastinum and pineal gland). "High levels of CCL17 have been found in SCs in seminoma tumours." (PMID 34440667, 2021).
skin atrophy (1 paper, 2025). The degeneration and thinning of the epidermis and dermis. "Meanwhile, prednisolone decreased the levels of histamine, IgE, CCL17, and CCL22 in plasma, but had adverse effects, such as lowering body weight, skin atrophy, and smaller spleens, compared to the NC." (PMID 39941059, 2025).
skin Paget disease (1 paper, 2023). "In skin Paget disease, the cells release soluble RANKL, improving the secretion of CCL5, CCL17, and CXCL10 from RANK+ M2 polarized TAMs, suggesting that Paget cells can modulate the microenvironment landscape by the stimulation of TAMs." (PMID 37958292, 2023).
synovitis (1 paper, 2018). Inflammation of a synovial membrane. "Since synovitis in OA is often associated with greater symptoms such as pain and joint dysfunction and may promote more rapid cartilage degeneration we explored a role for IRF4 and CCL17 in early synovitis in CiOA." (PMID 29622035, 2018). "CiOA synovitis in the absence of CCL17 suggests that CCL17 has other functions, apart from a chemotactic role." (PMID 29622035, 2018).
thyroid tumor (1 paper, 2019). A benign or malignant neoplasm affecting the thyroid gland. "Human monocytes exposed to CM from senescent thyrocytes and thyroid tumor cell lines undergo M2-like polarization, showing high CD206 and low MHC II markers, and upregulation of CCL17 secretion." (PMID 31113465, 2019).
tongue tumors (1 paper, 2021). "Therefore, we further validated the expression of Th1-associated chemokine genes, including Cxcl9, Cxcl10, and Ccl5, and Th2/Treg-associated chemokine genes, including Ccl17 and Ccl22, in carcinogen-induced tongue tumors using qRT-PCR." (PMID 33921389, 2021).
tuberculoid leprosy (1 paper, 2014). A principal or polar form of leprosy in which the skin lesions are few and are sharply demarcated. "Our findings highlight an association of increased dermal expression of CCL17 in the skin of patients with tuberculoid leprosy." (PMID 25412496, 2014). "Second, elevated dermal expression of CCL17 could occur following recruitment of a cell type that constitutively expresses CCL17 in patients with tuberculoid leprosy." (PMID 25412496, 2014). "Of the 24 soluble mediators of inflammation that were measured, 7 showed significant differences between lepromatous and tuberculoid leprosy (CCL2, CCL17, CCL18, IFNA1, IL10, IL22, and TNF)." (PMID 25412496, 2014).
urticaria (1 paper, 2016). A vascular reaction of the skin characterized by erythema and wheal formation due to localized increase of vascular permeability. "Positive associations were found between D-dimer and CCL27, CCL17, and CCL26 in our study, indicating that D-dimer and chemokine might play a concomitant role in the pathogenesis of urticaria." (PMID 27057079, 2016). "CCL11, CCL17, CCL26, and CCL27 are implicated in the pathogenesis of urticaria." (PMID 27057079, 2016). "In our study, serum levels of CCL11, CCL17, CCL26, and CCL27 increased significantly in both AU and CSU patients, indicating that elevated CCL11, CCL17, CCL26, and CCL27 are involved in the pathogenesis of urticaria." (PMID 27057079, 2016).
Whipple disease (1 paper, 2010). A systemic infection caused by the Gram-positive bacterium Tropheryma whipplei. "Arginase, the M2 chemokines Ccl22 and Ccl17, and the IL-1 receptor antagonist were induced in macrophage following infection as it has been described in Whipple's disease lesions." (PMID 20090833, 2010).
tumor (370 papers, 2010 to 2026). "Tumor-associated neutrophils expressing CCL2+ or CCL17+ promote BMP-2 and TGF-β2 secretion, thereby enhancing miR-301b-3p expression via paracrine signaling and activating the NF-κB signaling pathway." (PMID 38694506, 2024). "Increased expression of CCL17 derived from macrophages is also associated with larger tumor volume and enhanced invasiveness of PitNETs." (PMID 38716256, 2024). "In BC lymphocyte recruitment, CCL17/CCL22 acts as a ligand for CCR4, and CCL17/CCL22 is closely associated with Foxp3+ tumor-infiltrating regulatory T cells (Ti-Tregs)." (PMID 39329710, 2024). "The injection of neutralizing antibodies against CCL12 and CCL17 into tumors caused an explicit reduction in tumor size and pulmonary metastasis, with a drop in the migratory activities of TAMs and Treg cells." (PMID 38787372, 2024). "Among other notable DEGs, PD-L1+ clusters were also defined by high expression of many transcripts encoding for chemokines that have been shown to be released by suppressive tumor-associated neutrophils such as Ccl2, Ccl3, Ccl4, Ccl5, Ccl12, Ccl17, and Cxcl16." (PMID 39392875, 2024). "A high expression of CCL17 on TANs was also associated with increased tumor size, immunosuppressive macrophages, and regulatory T-cell (Tregs) migration." (PMID 39061147, 2024). "CCL2+ or CCL17+ tumor-associated neutrophils (TANs) were observed in the stroma of HCC, and conditioned media from TANs or recombinant CCL2 or CCL17 increased migration of macrophages and regulator T cells (Tregs)." (PMID 39682130, 2024). "For example, sorafenib treatment increases intratumoral infiltrating of F4/80+ tumor-associated macrophages, CD4+CD25+FoxP3+ regulatory T cells, CCL2+/CCL17+ tumor-associated neutrophils and CD11b+Gr-1+ myeloid cells in human and murine HCC models." (PMID 36906597, 2023). "We also found slightly elevated levels of CCL17, a chemokine that recently was shown to be expressed in tumor associated tissue resident macrophages of NSCLC and linked to chemoattraction, differentiation and proliferation of Tregs." (PMID 37404831, 2023). "Neutrophils in the tumor secrete CCL17, which directly causes the recruitment of Treg cells to the tumor microenvironment." (PMID 37686093, 2023). "Some studies have associated CCL17 with the N2 tumor-promoting subtype due to its role in immune suppression mediated by regulatory T cells." (PMID 37762335, 2023). "They found that the level of CCL17 is associated with an increased abundance of tumor-associated neutrophils." (PMID 37686617, 2023). "TARC (CCL17) is associated with neutrophil accumulation in tumors, the high infiltration of M2-like tumor-associated macrophages (TAMs), the accumulation of fibroblasts, and a decreased traffic of Treg." (PMID 36286054, 2022). "High expression of CCL17 in local tumors of NSCLC was found to be an important cause of Treg chemotaxis to tumor localization, causing suppression of the immune response." (PMID 35321241, 2022). "CCL17 is known to be released by tumor cells and tumor-associated macrophages, and promotes tumor development." (PMID 35682983, 2022). "In the TME, the core tumor cells as well as tumor-associated macrophages secrete high amounts of CCL22/CCL17." (PMID 35222362, 2022). "It indicates that the somatic cells in the CCL17 low-expression group had a higher degree of mutation and a higher tumor burden." (PMID 35321241, 2022). "In our experiments, we discovered that only M2 macrophages (tumor-associated macrophages) present in the TME express higher levels of CCL22/CCL17 than other macrophage subsets." (PMID 35222362, 2022). "CCL22 and CCL17 are released by tumor cells and tumor-associated macrophages, attracting CCR4+ Tregs to the tumor site." (PMID 35222362, 2022).